FXYD6 (FXYD domain containing ion transport regulator 6)
Description:
Associates with and regulates the activity of the sodium/potassium-transporting ATPase (NKA) which catalyzes the hydrolysis of ATP coupled with the exchange of Na(+) and K(+) ions across the plasma membrane. Reduces the apparent affinity for intracellular Na(+) with no change in the apparent affinity for extracellular K(+). In addition to modulating NKA kinetics, may also function as a regulator of NKA localization to the plasma membrane (By similarity).
Tractability: Small molecule: a structure with a bound ligand is known. Antibody: its Gene Ontology location is reachable by antibodies, with high confidence; UniProt places it where antibodies can reach, with medium confidence; UniProt predicts a signal peptide or a membrane-spanning region. PROTAC: ubiquitination databases record sites on it; its protein half-life has been measured.
Gene: Protein-coding gene on chromosome 11 (117,836,976 to 117,877,675, reverse strand). Ensembl gene ENSG00000137726.
Subcellular location: Cell membrane
Subcellular location (Human Protein Atlas): Cytosol; Nucleoplasm
Pathways (Reactome):
Disease: Potential therapeutics for SARS
Muscle contraction: Ion homeostasis
Transport of small molecules: Ion transport by P-type ATPases
Gene Ontology:
Molecular function: protein binding; sodium channel regulator activity; ion channel regulator activity
Biological process: establishment or maintenance of transmembrane electrochemical gradient; intracellular potassium ion homeostasis; intracellular sodium ion homeostasis; positive regulation of sodium ion export across plasma membrane; potassium ion import across plasma membrane; proton transmembrane transport; sodium ion export across plasma membrane; regulation of monoatomic ion transport
Cellular component: plasma membrane; membrane
Genetic constraint (gnomAD): Loss-of-function variants: 7 observed, 16.24 expected, observed/expected ratio (o/e) 0.43, 90% interval 0.24 to 0.81. The upper end of that interval is the gene's LOEUF score, 0.81, which puts it in group 3 of 6, group 1 being the genes least tolerant of losing a copy. Missense variants: 111 observed, 113.12 expected, observed/expected ratio (o/e) 0.98, 90% interval 0.84 to 1.15. Synonymous variants: 49 observed, 39.51 expected, observed/expected ratio (o/e) 1.24, 90% interval 0.99 to 1.57.
Homologues: Orthologues: chimpanzee FXYD6 (99% identical), rabbit FXYD6 (94% identical), mouse Fxyd6 (93% identical), dog FXYD6 (92% identical), rat Fxyd6 (92% identical), guinea pig FXYD6 (89% identical), tropical clawed frog fxyd6 (68% identical), zebrafish fxyd6 (63% identical). Paralogues in human: FXYD1 (45% identical), FXYD3 (34% identical), FXYD4 (33% identical), FXYD2 (29% identical), FXYD5 (24% identical), FXYD7 (23% identical).
Diseases named in the same sentence as FXYD6 in open-access papers:
FXYD6 is named in the same sentence as 37 diseases in open-access papers, as found by Europe PMC text mining. Sharing a sentence is not in itself a finding about the gene and the disease. The quoted sentences say what the papers report.
hepatocellular carcinoma (7 papers, 2014 to 2025). A malignant tumor that arises from hepatocytes. "Several investigations have indicated that FXYD6 is significantly expressed in cholangiocarcinoma and hepatocellular carcinoma." (PMID 40170843, 2025). "FXYD6 was also found to be upregulated in cholangiocarcinoma and hepatocellular carcinoma." (PMID 31803141, 2019). "Here, we demonstrate that FXYD6 is up-regulated in hepatocellular carcinoma (HCC) and enhances the migration and proliferation of HCC cells." (PMID 24715268, 2014). "Cartilage formation in the liver may cause progressive liver fibrosis, and downregulation of the FXYD6 and CORO6 genes in ALD‐induced mice may result in progression of hepatocellular carcinoma." (PMID 41190282, 2025).
schizophrenia (7 papers, 2007 to 2025). A major psychotic disorder characterized by abnormalities in the perception or expression of reality. "The FXYD6 gene is located at 11q23.3 in a schizophrenia-linked segmentand is associated with schizophrenia." (PMID 33817214, 2020). "FXYD6 gene mutation may affect the brain region and lead to schizophrenia." (PMID 35651949, 2022). "Several members of the FXYD family have been linked to major human diseases, including heart failure (FXYD1), hypomagnesemia (FXYD2), cancer (FXYD3, FXYD5), and schizophrenia (FXYD6), making them attractive specific targets for future therapies." (PMID 40428357, 2025). "With regard to the association between the FXYD6 gene and schizophrenia, no consistent conclusion has been reached." (PMID 24396454, 2014).
osteosarcoma (6 papers, 2014 to 2023). A usually aggressive malignant bone-forming mesenchymal neoplasm, predominantly affecting adolescents and young adults. "FXYD6 was defined as an oncogenic factor in osteosarcoma cells and is regulated by microRNAs, promoting cell proliferation, migration and metastasis." (PMID 34270462, 2021). "FXYD6 was identified as an oncogenic factor in osteosarcoma cells with higher expression levels than in normal tissues." (PMID 34270462, 2021). "Accordingly, the upregulation of FXYD6 reverses the tumor suppressing effects of these miRNAs in osteosarcoma." (PMID 31803141, 2019). "It has been known that FXYD6 is frequently up-regulated in cancer cells such as cholangiocarcinoma and osteosarcoma, and this higher level of FXYD6 can be targeted by miR-372-3p in osteosarcoma, thereby inhibiting the growth and metastasis of cancer cells." (PMID 34575133, 2021). "Because of this, FXYD6 has become a potential biomarker in osteosarcoma." (PMID 34575133, 2021).
cholangiocarcinoma (4 papers, 2014 to 2025). A carcinoma that arises from the intrahepatic biliary tree (intrahepatic cholangiocarcinoma) or from the junction, or adjacent to the junction, of the right and left hepatic ducts (hilar cholangiocarcinoma). "The results of this study indicate that FXYD6 may be a new biomarker for cholangiocarcinoma and may be associated with a favorable prognosis in this malignant disease." (PMID 24396454, 2014). "The results show that the positive expression rate of FXYD6 was significantly higher in cholangiocarcinoma than that in normal bile duct tissue (69 vs. 33.3%; P=0.002)." (PMID 24396454, 2014). "In the current study, the expression of FXYD6 was examined immunohistochemically in 72 cholangiocarcinoma tissues and 30 distal normal bile duct tissues matched with the tumors." (PMID 24396454, 2014). "Furthermore, the positive expression rate of FXYD6 in well- and moderately-differentiated cholangiocarcinoma was clearly higher than that in poorly-differentiated and mucinous cholangiocarcinoma (85.7 vs. 40%; P=0.000)." (PMID 24396454, 2014).
colorectal cancer (4 papers, 2019 to 2024). A primary or metastatic malignant neoplasm that affects the colon or rectum. "In cancer, FXYD6 was identified as positively associated with chemotherapy sensitivity in advanced colorectal cancer." (PMID 31803141, 2019).
mental disorder (2 papers, 2014 to 2019). A disease that has its basis in the disruption of mental process. "FXYD6 plays an important role in sensory organs such as the inner ear and is associated with various mental illnesses such as Alzheimer's disease." (PMID 31803141, 2019). "Except minor investigations showing the FXYD6 transcript was detected in human central nervous system and associated with some mental disorders, FXYD6 expression profile in other tissues, especially in tumor tissues, remains largly unknown." (PMID 24715268, 2014).
atherosclerosis (1 paper, 2022). A disease characterized by the build-up of fatty material and calcium deposition in the arterial wall resulting in partial or complete occlusion of the arterial lumen. "Through cell experiments, found that lncRNA up-regulated the expression of FXYD6, increased the uptake of cholesterol by macrophages, induced the production of inflammatory molecules, and promoted atherosclerosis." (PMID 35651949, 2022). "In the process of atherosclerosis, the expression of FXYD3 gene was significantly down-regulated, while the expression of FXYD6 was upregulated." (PMID 35651949, 2022).
Cirrhosis (1 paper, 2020). A chronic disorder of the liver in which liver tissue becomes scarred and is partially replaced by regenerative nodules and fibrotic tissue resulting in loss of liver function. "The positive expressionrate of FXYD6 protein was statistically higher in HBV-related HCC tissues thanthat in HBV-related cirrhosis or that in normal liver tissues." (PMID 33817214, 2020). "The FXYD6 mRNA in HBV-related HCC tissues was significantly higher than that inthe cirrhosis tissues or that in the normal liver tissues." (PMID 33817214, 2020). "The significant differences in FXYD6 expression between HCC tissues and thecorresponding cirrhosis indicated that the protein might be associated withcarcinogenesis of hepatocyte in cirrhosis." (PMID 33817214, 2020). "The results showed that FXYD6 was significantly associated withHCC, and FXYD6 mRNA and protein were upregulated in HCC compared with normal livertissue and HBV-related cirrhosis, indicating that FXYD6 may be a new biomarker andtherapeutic target for HCC." (PMID 33817214, 2020). "The aim of this studywas to investigate the expression of FXYD6 mRNA and protein in the malignant disease,paracancerous cirrhosis, and normal liver tissues and to analyze the relationshipbetween FXYD6 expression and clinicopathological features including MVI and earlyrecurrence." (PMID 33817214, 2020). "However, the expression of FXYD6 mRNA andprotein in HBV-related HCC with cirrhosis and the relationship between the proteinexpression and clinicopathological features in HCC remain elusive." (PMID 33817214, 2020). "Because the cirrhosis with HBVinfection was the leading factor of HCC in our country and the sample size was small inthe study, only the expression of FXYD6 protein and mRNA in HBV-related HCC withcirrhosis was studied." (PMID 33817214, 2020). "FXYD6 might be involved in hepatocyte carcinogenesis and tumor progression inHBV-related HCC with cirrhosis and indicated a poor prognosis." (PMID 33817214, 2020). "We examined FXYD6 protein immunohistochemically in 52 HBV-related HCC with cirrhosistissues, 28 distal non-cancerous cirrhosis tissues, and 15 normal liver tissues." (PMID 33817214, 2020).
glaucoma (1 paper, 2021). Increased pressure in the eyeball due to obstruction of the outflow of aqueous humor. "Three of them, ROR2, SDCCAG8, and FXYD6, are involved in molecular pathways that might have the slightest relation to glaucoma and are of potential interest for further investigations into their potential roles in glaucoma-related mechanisms." (PMID 34834521, 2021). "Since glaucoma is treated by lowering intraocular pressure, investigation of the involvement of the FXYD6 gene in glaucoma development may be worthwhile." (PMID 34834521, 2021).
glioblastoma (1 paper, 2023). The most malignant astrocytic tumor (WHO grade IV). "Additionally, FXYD6 was increased slightly in lower‐grade glioma (LGG), but significantly downregulated in glioblastoma (GBM)." (PMID 38093622, 2023).
glioma (1 paper, 2023). A benign or malignant brain and spinal cord tumor that arises from glial cells (astrocytes, oligodendrocytes, ependymal cells). "Undountedly, these results revealed that FXYD6 expression had a strong association with the activation of immunological functions to gliomas." (PMID 38093622, 2023). "The expression of FXYD6 in gliomas demonstrated a general association with the cliniopathological characteristics of gliomas, as observed in TCGA database." (PMID 38093622, 2023). "Meanwhile, FXYD6 expression was germane to its methylation, and thus we looked forward to constructing the diagnostic model to distinguish gliomas." (PMID 38093622, 2023). "Overall, the diagnostic model based on the methylation of FXYD6 CpG candidates could distinguish gliomas from non‐gliomas and LGG from GBM relatively accurately and stably." (PMID 38093622, 2023). "Hypermethylation of specific FXYD6 CpG sites in gliomas was identified, which could be used to build a diagnostic model." (PMID 38093622, 2023). "Methylation risk‐based model of FXYD6 could guide the treatment of glioma patients with TMZ and radiotherapy, thus making a contribution to health of human." (PMID 38093622, 2023). "Consistently, Kaplan–Meier (KM) curves showed that glioma patients with lower expression levels of FXYD6 or certain FXYD6 CpG sites with low methylation had bad prognosis." (PMID 38093622, 2023). "In this study, the enrichment of FXYD6 in CNS reminded us the pivotal role of it in the functions of nervous system, and we discovered down‐regulation of FXYD6 was pertinent to the growth and tumor microenvironment of glioma, especially GBM." (PMID 38093622, 2023). "Consistently, a FXYD6 methylation‐based prognostic model was constructed for glioma via LASSO Cox regression." (PMID 38093622, 2023). "This study aims to identify FXYD6 as a biomarker for glioma, by analyzing its expression and methylation patterns." (PMID 38093622, 2023). "FXYD6 is a promising biomarker for the diagnosis and prognosis of glioma, with its methylation‐based prognostic model serving as an independent factor." (PMID 38093622, 2023). "Then with glioma samples in TCGA database, FXYD6 expression was negatively correlated with the infiltration of macrophages M1, CD8 T cells and positively with monocytes." (PMID 38093622, 2023). "Next, the relationship of FXYD6 expression with the functional states in gliomas was explored, for instance, immune checkpoints, ferroptosis, EMT and pyroptosis." (PMID 38093622, 2023). "Glioma patients with higher FXYD6 expression showed significantly longer overall survival (OS) and progression‐free survival (PFS) than those with lower FXYD6 expression in TCGA database." (PMID 38093622, 2023). "Similaly, patients with high expression of FXYD6 had longer OS in primary and recurrent glioma patients of CGGA database." (PMID 38093622, 2023). "Clearly, glioma samples with high expression of FXYD6 had lower stromascore, immunescore, and estimatescore, which indicated FXYD6 expression was negatively correlated with the amout of immune and stromal proportion." (PMID 38093622, 2023). "Overall, FXYD6 was enriched in glioma stem cells and neuron, highly relevant to RNA splicing, cell junction, and various immunological functions in gliomas." (PMID 38093622, 2023). "The distribution of FXYD6 in gliomas futher displayed the down‐regulation in IDH wildtype, 1p/19q non‐codeletion, and un‐methylated MGMTp." (PMID 38093622, 2023). "In order to fathom the reasons for the bad prognosis of glioma patients with down‐regulation of FXYD6, we further explored the biological functions of FXYD6 in gliomas." (PMID 38093622, 2023). "The present study showed that FXYD6 was a novel biomarker for gliomas." (PMID 38093622, 2023). "Considering that FXYD6 is a member of FXYD family and natural endogenous inhibitor of NKA, and could promote TRPV1 activity, therefore, we wondered about the possible role of FXYD6 in gliomas." (PMID 38093622, 2023).
glioma (continued). "Hence, the present study suggests that FXYD6 holds potential as a valuable biomarker for the glioma diagnosis and prognosis." (PMID 38093622, 2023). "Through GO analysis and GSVA, FXYD6 was not only correlated with RNA splicing, cell junction organization and maintenance, synaptic membrane organization, histone binding, but multiple immunological functions in gliomas." (PMID 38093622, 2023). "Remarkably, it was positively correlated with drivers of ferroptosis and negatively with suppressors, implying FXYD6 might promote ferroptosis in gliomas which supported that the decreased immunological infiltration with the increase of FXYD6." (PMID 38093622, 2023). "A glioma detection model was developed using FXYD6 methylation data from TCGA and GEO." (PMID 38093622, 2023). "The findings indicated FXYD6 was connected with the RNA splicing, cell junction organization and maintenance, synaptic membrane organization, histone binding, and various immunological functions in gliomas." (PMID 38093622, 2023). "Furthermore, Cox regression analysis showed FXYD6 expression was an independent prognostic factor for the glioma patients, including various common prognostic items." (PMID 38093622, 2023). "Nevertheless, there was limited knowledge regarding the role of FXYD6 in gliomas." (PMID 38093622, 2023). "Moreover, FXYD6 was pertinent to the several classic EMT genes in gliomas (BMP2, TAB1, and so on) (|r| > 0.35, p < 0.05)." (PMID 38093622, 2023). "Finally, 10 FXYD6 CpG sites were selected to distinguish gliomas." (PMID 38093622, 2023). "Generally, downregulation of FXYD6 could act as an unfavorable biomarker for prognosis in gliomas." (PMID 38093622, 2023). "Meanwhile, the expression of FXYD6 was also relevant to ferroptosis, EMT and pyroptosis genes, all of which were possible to exert an effect on the progression of gliomas." (PMID 38093622, 2023). "Additionally, FXYD6 expression was generally negatively correlated with many classic inhibitory immune checkpoints, which suggested down‐regulation of FXYD6 might be involved in the inhibition of immune response to glioma cells." (PMID 38093622, 2023). "Meanwhile, for low expression of FXYD6 there was higher fraction of B cells naïve, CD8 T cells, and macrophages M1, yet less NK cells resting, and monocytes in gliomas (p < 0.05)." (PMID 38093622, 2023). "Identically, western blot also showed FXYD6 protein levels both in LGG (Grades II and III) and normal brain tissues were higher than those in Grade IV gliomas." (PMID 38093622, 2023). "Using TCGA and GTEx datasets, we analyzed FXYD6 expression in various tissues, confirming its levels in normal brain and different glioma grades via immunoblotting and immunostaining." (PMID 38093622, 2023). "On the other hand, distinctively, FXYD6 was extensively expressed and especially enriched in brain tissues no matter in gliomas or normal tissues." (PMID 38093622, 2023). "In summary, FXYD6 is downregulated in GBM, and could act as a biomarker of prognosis of glioma patients." (PMID 38093622, 2023).
Hypertension (1 paper, 2016). The presence of chronic increased pressure in the systemic arterial system. "This analysis allowed us to identify 6 well-annotated genes: RTP4, FXYD6, GDF11, IFNAR1, NOX3, and HLA-DQ2, associated with dynamics of future hypertension incidence." (PMID 27980621, 2016).
mucinous carcinoma (1 paper, 2014). "In CC tissues, the positive expression rate of FXYD6 was 41/61 (67.2%) for adenocarcinoma, 7/9 (77.8%) for papillocarcinoma and 0/2 (0%) for mucinous carcinoma." (PMID 24396454, 2014).
oligodendroglioma (1 paper, 2023). A well-differentiated (WHO grade II), diffusely infiltrating neuroglial tumor, typically located in the cerebral hemispheres. "Meanwhile, histology seemed related to FXYD6 expression, which was highest in Oligodendroglioma (O) and lowest in GBM." (PMID 38093622, 2023).
ovarian carcinoma (1 paper, 2025). A malignant neoplasm originating from the surface ovarian epithelium. "Nonetheless, the role and mechanism of FXYD6 in ovarian cancer have not been documented until now." (PMID 40170843, 2025).